CD81 (CD81 molecule)
Diseases named in the same sentence as CD81 in open-access papers (continued):
Sharing a sentence is not in itself a finding about the gene and the disease.
cancer (continued). "At the same time, CD81 is an important regulator of cancer cell growth and mobility, now considered as a valid target to combat different types of solid tumors and lymphoid malignancies." (PMID 37046846, 2023). "CD81, a transmembrane protein belonging to the tetraspanin family, has recently been suggested as a therapeutic target for cancers." (PMID 36979448, 2023). "Considering the important role of Linc01703-induced CD81+ exosome release, our findings provide new insights into the potential clinical application of CD81+ exosome-related cancer therapy." (PMID 38136327, 2023). "Tetraspanins, includingCD9, CD63, and CD81, are transmembranebiomarkers that play a crucial role in regulating cancer cell proliferation,invasion, and metastasis, as well as plasma membrane dynamics andprotein trafficking." (PMID 37307147, 2023). "For cancer tissues, the number of ductal epithelial cells increased; thus, the CD81 mean level was higher in cancer tissues than that of the NP." (PMID 37124494, 2023). "The CD81 interactome includes also the small GTPase Rac and the interaction plays roles in cancer cell motility and exosome formation." (PMID 37046846, 2023). "Among all human tetraspanins, the CD81 protein has been involved in some pathological conditions, particularly viral infection and cancer metastasis." (PMID 36979448, 2023). "Eleven of those proteins were detected in all patients, including the common EV markers CD9, CD63 and CD81, cancer-related markers CD24, CD29, CD44 and CD146, platelet markers CD41b, CD42a and CD62p as well as HLA-DR/DP/DQ." (PMID 35012489, 2022). "Overall, we demonstrated that the surface markers CD9, CD63, and CD81 are sufficient to distinguish between sEV populations derived from different cancer cells." (PMID 35955677, 2022). "Along with the upregulated CD9 levels on exosomes, the authors also found that αvβ3 integrin was also expressed in plasma exosomes of cancer patients, but the expression of another classic tetraspanin CD81 decreased somehow in cancer patients." (PMID 35757760, 2022). "Among these 16 proteins, proteins reflecting the cellular origin (HLA-DR, HLA-DP, HLA-DQ, CD31, CD41b, CD42a), activation markers (CD62p), EV markers (CD9, CD63, CD81), and cancer related markers (CD44 CD29, CD105, CD146) were found." (PMID 35012489, 2022). "We have performed IHC analysis for exosomal surface marker CD81 in OvCa tissues as exosomes participate in preparing a premetastatic niche (PMN) for the migrating cancer cells at the secondary site and promote metastasis." (PMID 35496046, 2022). "For the development of exosome-based early diagnosis and analysis of cancers, tetraspanins (such as CD9, CD63, CD81, and CD82) are typically utilized as the capturing molecules for the detection of cancer-associated exosomes." (PMID 33803846, 2021). "Several researches have revealed altered CD9 or CD81 expression in other types of cancer, but to date, little is known about the mechanisms which cause the changes of CD9 and CD81 expression during cancer initiation and metastasis." (PMID 32350244, 2020). "Future investigations will uncover a panel of available tetraspanins, including CD81, that can serve as markers for cancer stem cells in diverse epithelial tissues." (PMID 32444673, 2020). "Proteomic profiling of extracellular vesicles of 60 cancer cell lines (NCI-60) revealed CD81 expression in all 60, while CD9 and CD63 were expressed in about 40 of these cell lines." (PMID 29946318, 2018). "The top four associated diseases and disorders reflect a reported role of CD81 in cell migration and include organismal injury (33 molecules), cancer (28 molecules), inflammatory response (17 molecules) and infectious disease (15 molecules)." (PMID 30024968, 2018). "CD9, CD63 and CD81 are expressed in many different types of cells including neural cells, cancer cells and cancer stem cell lines." (PMID 25682864, 2015).
cancer (continued). "To begin to investigate the generality of the role of the CD9/CD81 complex in regulating α3β1 function, we also created CD9/CD81-silenced A431 carcinoma cells." (PMID 23613949, 2013). "CD81 is a cell surface protein that plays important roles in cancer." (PMID 41211316, 2025). "Given that LysoPCs have been reported to inhibit cancer cell proliferation and migration, their reduction in CD81+ Erys coculture conditions may represent an adaptive mechanism that favors AML progression." (PMID 41392984, 2025). "Interestingly, CD81 is involved in the regulation of cell migration and invasion, suggesting a role in cancer progression." (PMID 40411659, 2025). "In addition, the survival curves of OC patients with advanced cancer (stage III‐IV) showed the short PFS times along with high expression of CD81." (PMID 40604335, 2025). "CD81 plays a crucial role in cancer cell proliferation, invasion, and metastasis." (PMID 41211316, 2025). "Interestingly, the role of CD81 in the development of several other cancers is strikingly different." (PMID 40604335, 2025). "We seek to know how metformin induces exosome biogenesis and secretion in cancer cells; and found that the mRNA level of genes related to exosome biogenesis and secretion such as Alix, Rab27b, CD81, CD63, and Lamp-2 concomitantly with CD63 protein level up-regulated in cells treated with metformin." (PMID 38627767, 2024). "Moreover, CD9 was enriched in “immune system;” CD63 was enriched in “transport and catabolism” and “cancers: overview;” CD81 was enriched in “infectious diseases: parasitic,” “infectious diseases: viral” and “immune system” by KEGG pathway analysis." (PMID 38725025, 2024). "Exosomes carry specific proteins (CD9, CD81, CD63, ALIX, TSG101, and HSP70), nucleic acids (DNA, miRNA, lncRNA, and circRNA), lipids, and metabolites with cancer information, making them potential cancer diagnostic biomarkers." (PMID 37016296, 2023). "Indeed, while CD81 is highly expressed on CD81+migcDC1s, it can also be expressed on cancer cells and other immune cells, such as Tregs and CD11b+GR1+ cells." (PMID 37622122, 2023). "Thus, we propose these CD81-BPs with the anti-migration property against cancer cells for the development of novel therapeutic strategies." (PMID 36979448, 2023). "Consequently, our observations provide new insights into the potential clinical application of CD81+ exosome-based cancer therapy." (PMID 38136327, 2023). "Blocking CD81 could limit virus-entry, cancer cell proliferation and invasion, inflammatory processes and metastasis, for example." (PMID 37046846, 2023). "Moreover, the inhibitory mechanism of CD81-BPs for cancer cell migration and in vivo assays should be considered." (PMID 36979448, 2023). "There are 4 genes (UACA, PTTG1IP, PIGR, CD81) of this GO term may interacted with ACTR2, EIF6 and hsa-miR-139-5p at the same time, and they play an important role in cancer associated pathway: apoptotic process (UACA, PTTG1IP) and immunity (PIGR, CD81)." (PMID 37365497, 2023). "Meanwhile, recent studies have disclosed the role of CD81 in cancer immunomodulation." (PMID 33919192, 2021). "For the specific characterization by flow cytometry and confocal microscopy, different commercial antibodies against selected receptors were used, including the general tetraspanins CD9, CD63 and CD81, and cancer-related receptors (CD24, CD44, CD54, CD326 and CD340)." (PMID 32054015, 2020). "Some previous studies have shown that CD9 and CD81 are involved in cancer." (PMID 32350244, 2020). "Intriguingly, the suppression of some of the identified immune response genes, including CD81, might contribute to the suppression of cancer cells migration and invasive capacity." (PMID 33381110, 2020).
cancer (continued). "They analyzed the expression of three exosomal markers (CD9, CD81, and CD63), showing a mean concentration higher for CD63 and lower for CD9 and CD81 between cancer patients and healthy individuals, although significant statistical differences were observed only for CD81 levels." (PMID 29890622, 2018). "Moreover, this protein-protein interaction network also indicated that HNRNPK was physically interacted with many other critical cancer associated genes such as EGFR, CD81 and AURKA." (PMID 29262567, 2017). "On the other side, CD81 is a specific exosomal membrane protein, suggesting that exosomes derived from cancer cells may play a crucial role in mediating communication between cancer cells and TAMs." (PMID 40604335, 2025). "However, the role of EVs in cancer development and its association with CD44 and CD81 functions remain unclear." (PMID 36193887, 2022). "Besides promoting HCV transfection, CD81 has a predicting value in cancer development." (PMID 33919192, 2021). "Recently, it has been shown that CD81 may be involved in cancer cell proliferation and metastasis." (PMID 31494861, 2019). "The binding interactions between immobilized antibodies and EVs isolated from different cancer cell lines revealed a unique SPR molecular fingerprint (SPR-MFP) consisting of varying expression levels of the CD9, CD63 and CD81 EV biomarkers, as well as CXCR4." (PMID 41892066, 2026). "The use of ELISA-based methods for the quantification of proteins specific to cancer-derived exosomes, such as CD44, CD44v6, CD9, EpCAM, and CD81, has been well-documented." (PMID 41573685, 2025). "Previous research has demonstrated that TSPAN proteins, like CD9, CD81, CD151, and TM4SF1, promote cancer metastasis by interacting with integrin α3β1 or α6, which aligns with our functional enrichment results." (PMID 41347075, 2025). "It should be noted that the same proteins (CD9, CD24, CD63, CD81, MMP9) were common to exosomes of cancer cells and primary cells." (PMID 40310419, 2025). "Taken together, conjoint analysis of multiomics in our study was applied to discover the vital signalling pathway mediated by CD81 and deepen our understanding of PCS between cancer cells and TAMs." (PMID 40604335, 2025). "Our previous studies demonstrated that cancer cell-derived extracellular vesicles (EVs) and their surface proteins CD44 and CD81 contribute to the modulation of the microenvironment and EV-recipient cells." (PMID 40818975, 2025). "Most of them measured either cancer-related proteins (i.e., PSMA, PCA3, TMPRSS2:EGR, or PSA) or exosomal cell surface proteins (CD9, CD3, EpCAM, or CD81)." (PMID 39859516, 2025). "Lastly, these results suggest that EVs from cancer cells and stem cells display cell type-specific expression of CD63, CD9, and CD81." (PMID 38786083, 2024). "To compensate, we validated and included common surface proteins found in most cancer types, like CD9, CD81, and human epidermal growth factor receptor 2 (HER2)." (PMID 38326078, 2024). "CD81, CD9, TSPAN31, and TSPAN13 are also reported to facilitate cancer cell invasion and metastasis." (PMID 36941633, 2023). "The following TSPANs have been involved in enhancing cancer therapy resistance: CD9, CD81, TSPAN1, TSPAN3, TSPAN31, CD82 and CD63." (PMID 36941633, 2023). "Many of these tetraspanins are involved in cancers, chiefly TSPAN1, TSPAN8, TSPAN 13, CD9, CD37, CD63, CD81, CD82 and CD151." (PMID 37046846, 2023). "After characterization of CD81-BP candidates, their inhibition effect on MDA-MB-231 cancer cell migration was later demonstrated in the Boyden chamber assay." (PMID 36979448, 2023). "Pie charts represent the expression profiles of CD9, CD81 and CD63 in percentage of circulating EV particles from representative cancer patients and LC control." (PMID 36582804, 2022). "The number of 6 μm size fraction of cancer-derived EVs correlated negatively with the CD63 and CD81 expression in NTHY cells, as well as positively with angiogenesis in vitro." (PMID 35328683, 2022).
cancer (continued). "The common exosome markers, including CD63, CD81, and CD9 and the cancer marker EGFR, are detected in A549 cell-derived exosomes with a Western Blot." (PMID 34769444, 2021). "In other cancers, such as oral cancer, exosomal tetraspanins CD9, CD63, and CD81 can be potential biomarkers for early diagnosis in high-risk patients before any clinical symptoms." (PMID 34540692, 2021). "EVs were isolated from 80 serum samples from healthy individuals and cancer patients via polyethylene glycol (PEG)-based precipitation and immunoaffinity separation using antibodies against CD9, CD63, CD81, and EpCAM." (PMID 33808296, 2021). "Based on the available evidence, CD81 and CD82, and TSPAN6 can serve as cancer suppressors, while CD151, TSPAN1, and TSPAN8 act as cancer promoters in the diagnosis and prognosis of HCC patients." (PMID 34540692, 2021). "Various exosome types circulate in the blood of healthy donors and patients with different cancers, and surface proteins mainly represented by CD9, CD24, CD63 and CD81 are considered as universal markers of blood exosomes." (PMID 32218180, 2020). "We quantified by an ELISA-based technique specific proteins of cancer-derived exosomes (CD44,CD44v6,EpCAM,CD9,CD81,Tspan8,Integrin α6,Integrin β4,CD24,CXCR4)." (PMID 31048929, 2019). "Among the human tetraspanins, Tspan8 and 12, CD9, CD37, CD63, CD81, CD82, and CD151 play a role in cancer progression." (PMID 29946318, 2018). "The cell surface expression of other tetraspanin members that play prominent roles in cancer cell invasion including CD63, CD81, and CD151 were unaffected by CD9 overexpression." (PMID 23840773, 2013). "The panel of antibodies contained the well-known exosome markers (CD9, CD63, CD81 and HLA-ABC) and 17 other membrane markers and antigens related to, for example, cancer and inflammation." (PMID 26082317, 2013). "Our findings build on this emerging evidence and suggest that PTGFRN may serve as a pan‐cancer marker of EVs derived through non‐canonical, ESCRT‐independent pathways—distinct from the classical CD9‐, CD63‐, or CD81‐marked small EVs." (PMID 41039818, 2025). "Western blotting revealed CD9, CD81, and CD63 in normal and cancer Exos." (PMID 39206404, 2024). "Furthermore, it has been observed that both CD81 and CD82 influence cytokine production in CD4 cells and affect cytotoxicity against cancer cells in CD8 cells." (PMID 38515751, 2024). "Therefore, in this study, our aim was to screen CD81-binding peptides (CD81-BP) from the amino acid sequence of the EWI-2 protein and to assess their impact on cancer cell migration." (PMID 36979448, 2023). "Notably, a transmembrane ubiquitin ligase family member MARCH8 has been associated with lysosome degradation of both CD44 and CD81 in fibroblast cells and/or TNBC cells, suggesting CD44 and CD81 might follow similar fates of protein degradation or recycling in both cancer cells and other cells." (PMID 36193887, 2022). "So far, very few studies have investigated three tetraspanins (CD63, CD9, and CD81) together in clinical settings; therefore, it is still unclear whether the level of CD9, CD63, or CD81 correlates with different types of cancers." (PMID 35757760, 2022). "CD81 and CD44 are required for exosome-induced cancer stemness." (PMID 36193887, 2022). "Although CD81 is not ubiquitously expressed on every exosome, CD81 expressions are common in different cancer EXOs." (PMID 34361239, 2021). "Calibration curves were generated with two most effective combinations (anti‐CD9/Banti‐CD81 and anti‐CD63/Banti‐CD9), resulting in 103 and 104 times higher sensitivity than the EV concentration in human blood plasma from healthy or cancer patients, respectively." (PMID 33664936, 2021).
cancer (continued). "Cancer-associated exosomes opt to transport specific transmembrane proteins, including integrins and tetraspanins such as CD9, CD63, CD81, and CD82 that are specifically recognized by target cells, which can explain the high rate of exosomal uptake by cancer-adjacent stromal cells." (PMID 32121073, 2020). "In general, PCa-associated exosomes procured from clinical samples reveal cargo that contains cancer-related proteins such as CD9, CD81, and TSG101, Annexin A2, Fatty Acid Synthase (FASN), and prostate-specific membrane antigen (PSMA: a PCa-specific biomarker)." (PMID 32121073, 2020). "Cancer EVs normally have the same set of surface markers to those of healthy cells, being indistinguishable from their normal counterparts, although CD9 and CD81 overall seem to be more abundant, but mutually exclusive, on cancer EVs." (PMID 31877735, 2019). "But other proteins like CD81, CD63 and ALIX showed a dramatic difference between the two groups and also differed significantly from the MDA-231 derived exosomes, hinting towards a HepN mediated cancer cell transformation." (PMID 29137633, 2017). "In pathological conditions such as cancer, variation in the expression level of CD9 or CD81 may induce dramatic effects on cell motility through a change in the membrane compartmentalization of CD9P-1, thus favoring metastasis." (PMID 20574531, 2010). "Interestingly, the immunomagnetic separation of the exosomes based on CD81 is not affected by the serum (even if it is undiluted), which can be easily detected by an electrochemical immunosensor using cancer related biomarkers, such as CD24 and CD340." (PMID 32054015, 2020). "Therefore, our results indicated that reduced expression of CD9 and CD81 in HCC may activate JNK signaling pathway, which promotes cancer cell proliferation via regulating the downstream genes such as Cyclin D1 and Bcl-2." (PMID 32350244, 2020). "A multitude of evidence revealed that distinct exosomal proteins, e.g., Rab, GTPases, ESCRT, CD9, CD81, CD63, flotillin, TSG101, ceramide, Alix, tetraspanins, and integrins, could be used for cancer detection and consideration of clinical outcomes in cancer patients." (PMID 33168028, 2020). "In general, the EV levels of CD9, CD81 and CD151 were increased in OC and B samples compared with Ctrl and PD samples, which could be due to samples being obtained from two different biobanks, but increased levels of EVs have previously been reported in cancer patients." (PMID 40372993, 2025). "However, no clinical application of CD81 inhibition in cancer has been explored." (PMID 33919192, 2021). "Materials and methods: A novel protein array based on biotin-labelled anti-tetraspanin (CD9, CD63 and CD81) antibodies specific for exosomes in general enabled capture of exosomes from crude human donor plasma and MV preparations from stable isotope-labelled cancer cells and synovial fluid." (PMID 26082317, 2013). "To evaluate the correlation between CD81 and disease progression, we used TISIDB database and found that CD81 expression showed an upward trend with cancer staging, but without significance (p = 0.0897)." (PMID 40604335, 2025). "sEV enrichment was verified by transmission electron microscopy and western blotting using antibodies against ALIX, TSG101, CD63, CD81, CD9 (sEV markers), and also against GRP94 (negative control), HSP70 (cancer biomarker), and PD-L1." (PMID 37973956, 2024). "Similar results were obtained in A431 carcinoma cells, indicating that the ability of CD9/CD81 to regulate α3β1 integrin is not restricted to the MDA-MB-231 model." (PMID 23613949, 2013).
hematological malignancies (4 papers, 2010 to 2024). "CD81 stands out as a significant marker in characterizing hematological malignancies." (PMID 39329950, 2024).
infectious disease (3 papers, 2018 to 2024). A disorder directly resulting from the presence and activity of a microbial, viral, or parasitic agent in humans. "The two top ranked cellular networks associated with the CD81 interactome in liver cells are cell-to-cell signaling and movement (score 36, 18 focus molecules) and infectious disease (score 16, 10 focus molecules)." (PMID 30024968, 2018). "To ensure that HEO could be applied as a model of infectious diseases, we examined the expression of CD81, an important receptor for Plasmodium falciparum sporozoites and hepatitis C virus." (PMID 33133779, 2020).